APC (APC regulator of Wnt signaling pathway)
Diseases named in the same sentence as APC in open-access papers (continued):
Sharing a sentence is not in itself a finding about the gene and the disease.
tumor (continued). "About 60-80% of CCs develop on the basis of a dysregulation of the Wnt/β-catenin signalling pathway triggered in most cases by mutations in the tumour suppressor gene APC (adenomatous polyposis coli) which is indicated by an accumulation of β-catenin in the tumour cells." (PMID 22168803, 2011). "Thus, in the FAP-associated desmoid tumours from individuals carrying a germline APC mutation, complete APC inactivation through loss of the second, wild-type allele was a relatively frequent event (29%)." (PMID 21931686, 2011). "Firstly, deregulation of many proteins such as deficiency of myosin light-chain phosphorylation, overexpression of Aurora A, and mutation/inactivation of many tumor suppressers such as APC, BRCA1, and LATS2 could induce tetraploid cells." (PMID 22076149, 2011). "Tumours were scored as APC mutated if they carried at least one clearly deleterious APC mutation (mutations leading to premature termination and missense mutations found in CRC but not in the corresponding mucosa, absent from dbSNP and predicted to be pathogenic - a total of 103 mutations)." (PMID 21901162, 2011). "All MEN1 mutated tumours in the current study displayed APC promoter 1A hypermethylation, and a weak but significant correlation (Pearson's correlation 0.322, p = 0.027) was revealed between high APC methylation density and presence of an MEN1 mutation." (PMID 20208994, 2010). "Mutations in either β-catenin or APC can distort the normal tumor suppressive effect of APC." (PMID 20029639, 2009). "Additional supporting evidence for our model was recently provided by studies comparing tumour formation in Min/+ mice (with a heterozygous nonsense mutation in the APC gene that leads to constitutive activation of the canonical Wnt pathway) with different Tiam1 backgrounds." (PMID 18826597, 2008). "On the whole, the evidenceno longer supports the hypothesis that activation of PPARγ promotes tumor formation in mice with germline APC mutations." (PMID 18615192, 2008). "Although genetic changes (e.g. APC mutations) cannot be reversed during tumour progression, other effects may show plasticity when selection pressure is lost due to mutations in other pathways." (PMID 18414471, 2008). "The activity of the Wnt/β-catenin signaling pathway might account forthese seemingly discrepant results, as tumor models generated by APC mutationor polyoma middle T antigen all involve overly active Wnt/β-catenin signaling." (PMID 18784849, 2008). "Indeed, the vast majority of sporadic colorectal cancer cases is caused by constitutive Wnt activation due to mutations in either the APC tumour suppressor or the β-catenin (CTNNB1) oncogene." (PMID 18506144, 2008). "Apoptotic activity induced by two 20 Gy radiotherapy protocols applied to APC-mutated tumor cells." (PMID 16472396, 2006). "Seventeen percent of tumours harboured both an APC and a K-ras mutation (109/656)." (PMID 16356174, 2005). "Tumours that display mismatch repair deficiency, may form a distinct sub-group as they differ from tumours with APC and/or K-ras mutations with regard to age, sex, tumour sub-localisation and differentiation." (PMID 16356174, 2005). "APC mutations were the most frequent, found in 88% of cases, with a predominance of nonsense mutations (56.6%), frame shift deletions (28.3%), and multi-hit events, consistent with its role as a truncating tumor suppressor and negative regulator of WNT signaling." (PMID 40940930, 2025).
tumor (continued). "Additionally, a group of genes from cluster 5, identified with the Natural Language Processing (NLP) clustering analysis, showed a link with tumor suppressors, e.g., the APC gene that, through association with other proteins, prevents the uncontrolled growth of cells." (PMID 40724805, 2025). "Regarding the potential practical application of the current findings in precision medicine, our data suggest that, based on the STR somatic mutation status of BRAF and APC in the BCC tumor tissue, it may be possible to select a group of patients who may respond well to some of the targeted therapy." (PMID 40427167, 2025). "Finally, focused investigation of how the altered poly(A) site selection driven by APC loss influences tumorigenesis and tumor phenotypes may yield new insights into the process of cellular transformation." (PMID 39375704, 2024). "Moreover, IL-33 produced by non-tumor epithelial cells has been shown to drive colorectal cancer tumorigenesis in APCMin/+ mice, which serve as an excellent model for colorectal tumors due to a mutation in the APC gene, a significant tumor-suppressor gene in the Wnt signaling pathway." (PMID 40236667, 2024). "Second, in our exploratory analysis aimed at uncovering the connection between APC mutations and aberrant β-catenin expression, our results revealed a compelling coexistence between APC mutations and aberrant nuclear β-catenin expression within the same tumor samples." (PMID 38414697, 2024). "Therefore, SR‐B1 protein may interact with APC protein through the lipid metabolism, immune systems, and tumor‐associated proteins." (PMID 37766594, 2023). "It is well established that variants in the APC gene are implicated in the regulation of the intracellular level of beta-catenin through the Wingless/Wnt signal transduction pathway and have been implicated in carcinogenesis through loss of tumour suppressor activity." (PMID 37277882, 2023). "Although popular models suggest that β-catenin phosphorylation/ubiquitination should be inhibited by APC mutations, it has been documented that different APC mutation types have different degradation efficiencies for β-catenin, which contributes to different levels of tumor progression." (PMID 36878899, 2023). "Similarly, whilst the non-coding (deep intronic) BAP1 variant was identified in a family with a history of BAP1-related tumours, the second non-coding APC promoter variant was identified in an index case with a phenotype not consistent with the typical presentation, as previously reported." (PMID 37723522, 2023). "Furthermore, the decreased scores for APC co‐inhibition in the low‐risk group might indicate reduced levels of immune checkpoint molecules, which are often hijacked by tumours to evade immune surveillance." (PMID 38146607, 2023). "However, patients in the high-risk group exhibit a low mutation rate of APC, suggesting that APC may be a tumor suppressor gene." (PMID 35748788, 2022). "Another aspect requiring careful consideration is that family history may also be associated with rare variants with high penetrance (e.g., mutations of APC tumor suppressor genes and DNA mismatch repair genes), whereas PRSs are built on the basis of common risk variants with low penetrance." (PMID 36476570, 2022). "Simultaneous existence of BRAF missense mutation and an APC truncation was rarely observed, which further supported the hypothesis that the most important oncogenic driver events differed between Wnt‐low and Wnt‐high tumor groups." (PMID 35904277, 2022).
tumor (continued). "Because APC is a multidomain protein and serves multiple functions through binding with different partners, it is possible—and some data suggest—that some form of C-terminally truncated APC proteins may have gain-of-function properties beyond the well-established loss of tumor-suppressive function." (PMID 35141142, 2021). "Indeed, aberrant Wnt signalling underpins colorectal cancer (CRC) initiation and progression in humans, with loss-of-function mutations in the APC tumour suppressor gene reported in >80% of sporadic cases and germline mutations predisposing to familial adenomatous polyposis." (PMID 33673710, 2021). "Moreover, we found that the loss of APC also resulted in tumor formation in a xenograft model." (PMID 33808166, 2021). "However, the APC tumor suppressor mutation can save β-catenin." (PMID 33920054, 2021). "Moreover, the blockade of WNTs/RSPOs inhibits the growth of tumor cells that harbor APC mutations." (PMID 33291655, 2020). "This approach identified 24 mutations in 18/25 (72%) tumour samples across these regions of the APC gene, a notably higher rate than some previous studies looking at APC mutation in early-onset CRCs that may, in part, reflect the extent of APC gene coverage by the methodology used here." (PMID 33352971, 2020). "Therefore, the individual changes were interpreted as tumor-related somatic variants, and the germline involvement of the APC gene in the evaluated patients could be excluded." (PMID 31963551, 2020). "Notably, both S100 and APC are implicated in tumor progression." (PMID 32055236, 2020). "To determine whether Trp-related genes are induced during the initial steps of cellular transformation, we compared HCECs and HCECs transformed by the expression of a mutant form of APC that leads to its loss of its tumor suppressive function: the activation of the WNT pathway." (PMID 31416966, 2019). "Moreover, although WNT signaling is activated by APC mutations in FAP neoplasms, reduced inactivation of OTX2 and activation of MYC may contribute to tumor development in FAP." (PMID 30220972, 2018). "In addition, 21 novel somatic variants were identified in the tumor samples, among which 7 mutations were frameshift alterations located in the central part of the APC gene, which may alter the function of the APC protein." (PMID 27121310, 2016). "Notably, adding metastasis led to a significant HR for two-hit APC mutation tumours (HR=1.58, χ2P=0.027, Model 3) but decreased the HR of AKP from 1.79 (χ2P=0.005, Model 2) to 1.43 (χ2P=0.090, Model 3) probably because of the very strong correlation of AKP with distant metastasis." (PMID 27302369, 2016). "There is no surprise that early study showed genetic events, including APC mutation and β-catenin activation may lead to barrier function loss in colonic epithelium and result in a translocation of microbial products into the tumor microenvironment." (PMID 26760960, 2016). "The number of APC mutations we observed here was slightly lower than estimates from the TCGA, who report frequencies of 60–80% for hypermutated and non‐hypermutated cancers, respectively, and probably reflects the difficulties of identifying somatic mutations in lesions with low tumour cellularity." (PMID 26414517, 2016). "Finally, mitochondrial APC has been associated with tumor survival by regulating Bcl2." (PMID 23844091, 2013). "What’s more, there are evidences to believe that GSTP1 methylation could trigger “epigenetic catastrophe” which involves hypermethylation of associated genes including APC (a tumor suppression gene), and RAR-beta (tumor suppressor gene involved in cell cycle and apoptosis)." (PMID 24086370, 2013). "The increased occurrence of CNAs in FAP-associated tumours with mutations in the APC gene versus the reduced occurrence in sporadic tumours harbouring mainly β-catenin gene mutations is in agreement with the notion that loss of the mitotic function of APC may lead to chromosomal instability." (PMID 21931686, 2011).
tumor (continued). "Thus Cdc42 may lead to degradation of APC mutants and this may potentially increase the tumor susceptibility of the cells." (PMID 21311754, 2011). "The complex in the canonical Wnt pathway formed by β‐catenin includes tumour suppressors axin and APC, as well as two types of Ser‐Thr kinases: CK1α/δ and GSK3α/β." (PMID 41578162, 2026). "The identification of a previously unrecognized APC/PTPN13/STAT1-dependent tumor immune-suppressive mechanism in this study represents a significant advance, offering a compelling strategy for development of therapeutic interventions for CRC." (PMID 41486293, 2026). "In subcutaneously grafted tumor models, ΔN-β-catenin overexpression showed a minimal impact on tumor growth and CD8+ T cell infiltration compared with APC knockout, which significantly increased tumor growth and reduced CD8+ T cell infiltration." (PMID 41486293, 2026). "Analysis of tumor-infiltrating lymphocytes (TILs) using H-2Kb-OVA257-264 tetramer staining revealed that APC knockdown led to a marked reduction in antigen-specific CD8+ T cells." (PMID 41486293, 2026). "An example is Fusobacterium nucleatum, which increases expression of the oncogenic miR-135b/miR-21, thereby inhibiting the expression of the tumor suppressors APC/PTEN and stabilizing β-catenin." (PMID 41676338, 2026). "These miRNAs can drive tumor progression by activating the canonical Wnt/β-catenin signaling pathway through APC suppression, as demonstrated in other tumor models." (PMID 41511367, 2026). "Two APC mutations, C1270* and H1490fs23, were also identified in the tumor next generation sequencing test, indicating biallelic inactivation of APC, in which C1270* is of germline origin." (PMID 40491286, 2026). "In human CRC, it is notoriously difficult to deconvolute the order of early clonal driver events such as APC and KRAS mutations from sequencing data derived from bulk tumour samples." (PMID 41339549, 2026). "The functional role of miR-142-3p/5p in regulating cellular proliferation and tumor development can be mediated by the canonical Wnt/β-catenin signaling pathway through APC repression." (PMID 41511367, 2026). "miR-182 promotes tumor growth and invasion by the potential target of APC and tumor suppressors like MITF." (PMID 40282456, 2025). "xStAx-VHLL effectively inhibits the Wnt signaling of cancer cells and APC−/− organoids and reduces the tumor burden in BALB/c nude mice by targeting β-catenin for efficient degradation." (PMID 40649987, 2025). "Somatic mutations in APC gene, a key regulator of the Wnt/β-catenin pathway, occur in approximately 70–80% of CRC cases and contribute to tumor progression." (PMID 40429703, 2025). "As an upstream regulator of MEK/ERK and Wnt/β-Catenin signaling in intestinal cancers, STRAP plays an important role in promoting APC-induced tumor development and progression." (PMID 40558481, 2025). "The tumor suppressor activity of APC relies crucially on its 20AARs domains, which bind and target β-catenin as an essential part of the β-catenin destruction complex." (PMID 41091816, 2025).
tumor (continued). "Therapeutic approaches targeting APC/Wnt signaling are currently in development but remain largely indirect, given the difficulty of restoring tumor-suppressor function." (PMID 41228231, 2025). "The assessment of the cancer genome profile revealed the stability of microsatellite status, a tumor mutation burden of 4 mutations per megabase (Muts/Mb), alterations in TSC1 and APC, and amplification of ERBB4." (PMID 39846235, 2025). "A defining strength of AI-HOPE-WNT lies in its ability to dynamically stratify CRC patient cohorts by WNT gene mutation status (e.g., APC, AXIN1/2, RNF43), tumor location, age group, treatment exposure (e.g., FOLFOX), and molecular phenotype (e.g., MSI)." (PMID 40860720, 2025). "By negatively regulating canonical Wnt signaling, APC is able to promote differentiation, counteract proliferation, facilitate apoptosis, and suppress invasion and tumor progression." (PMID 40943055, 2025). "Tumor-suppressor genes, including APC, BARD1, HMMR (RHAMM), KLLN, LZTR1, MCPH1 (BRIT1), MLH1, NF1, RB1CC1 (FIP200), SLC22A18, and SPTBN1, have been found to increase the risk of disease and tumor development." (PMID 40941673, 2025). "Loss-of-function mutations in the oncosuppressor APC, mutations in CTNNB1 (β-Catenin gene), and the excessive presence of Wnt ligands in the tumor microenvironment (TME) disrupt these regulatory mechanisms, resulting in uncontrolled tumor growth." (PMID 40722631, 2025). "RNA-seq analysis revealed a substantial decrease in APC expression in the tumor sample (tumor fragments per kilobase of transcript per million fragments mapped (FPKM): 0.296 vs. normal FPKM: 2.262)." (PMID 40113261, 2025). "In all tumor samples from FAP patients with an APC germline variant, somatic mutations in the APC were frequently observed (76%)." (PMID 41488735, 2025). "A previous study highlighted CtBP’s tumor suppressor functions by direct binding to APC’s C-terminal, reducing free β-catenin availability." (PMID 39977302, 2025). "In several tumor samples, extremely increased methylation was observed around exon 1A of APC and exon 1 of MLH1." (PMID 40004106, 2025). "This approach allowed us to identify differentially expressed genes in APC Min/+ mice during the late stages of intestinal tumorigenesis and track how tumor-related gene expression changes over time." (PMID 41009818, 2025). "Mutations in APC, AXIN1, and CUX1 are known to promote tumor aggressiveness, stemness, and metastatic dissemination." (PMID 40842629, 2025). "In recent work, Vivian Li’s team uncovered a rare SOX2-positive cell population in APC-mutated CRC that drives cellular plasticity, promoting tumor progression and drug tolerance." (PMID 41221269, 2025).